RN7SL402P (RNA, 7SL, cytoplasmic 402, pseudogene)
Gene: Miscellaneous RNA gene on chromosome 19 (35,881,890 to 35,882,153, forward strand). Ensembl gene ENSG00000243968.
Homologues: Orthologues: chimpanzee Metazoa_SRP (97% identical), macaque Metazoa_SRP (87% identical), dog Metazoa_SRP (69% identical). Paralogues in human: RN7SL1 (81% identical), RN7SL2 (81% identical), RN7SL3 (80% identical), RN7SL660P (79% identical), RN7SL296P (78% identical), RN7SL597P (78% identical), RN7SL301P (78% identical), RN7SL586P (78% identical), RN7SL493P (78% identical), RN7SL11P (77% identical), RN7SL666P (77% identical), RN7SL218P (77% identical), and 698 more.